EIF3B (eukaryotic translation initiation factor 3 subunit B)
Description:
RNA-binding component of the eukaryotic translation initiation factor 3 (eIF-3) complex, which is required for several steps in the initiation of protein synthesis. The eIF-3 complex associates with the 40S ribosome and facilitates the recruitment of eIF-1, eIF-1A, eIF-2:GTP:methionyl-tRNAi and eIF-5 to form the 43S pre-initiation complex (43S PIC). The eIF-3 complex stimulates mRNA recruitment to the 43S PIC and scanning of the mRNA for AUG recognition. The eIF-3 complex is also required for disassembly and recycling of post-termination ribosomal complexes and subsequently prevents premature joining of the 40S and 60S ribosomal subunits prior to initiation. The eIF-3 complex specifically targets and initiates translation of a subset of mRNAs involved in cell proliferation, including cell cycling, differentiation and apoptosis, and uses different modes of RNA stem-loop binding to exert either translational activation or repression. (Microbial infection) In case of FCV infection, plays a role in the ribosomal termination-reinitiation event leading to the translation of VP2.
Synonyms: EIF3S9; PRT1; EIF3-ETA; EIF3-P110; EIF3-P116
Tractability: Small molecule: a structure with a bound ligand is known. PROTAC: ubiquitination databases record sites on it; its protein half-life has been measured.
Gene: Protein-coding gene on chromosome 7 (2,354,086 to 2,380,747, forward strand). Ensembl gene ENSG00000106263.
Subcellular location: Cytoplasm; Cytoplasm, Stress granule
Subcellular location (Human Protein Atlas): Cytosol; Nucleoplasm
Pathways (Reactome):
Metabolism of proteins: Formation of a pool of free 40S subunits; Formation of the ternary complex, and subsequently, the 43S complex; GTP hydrolysis and joining of the 60S ribosomal subunit; L13a-mediated translational silencing of Ceruloplasmin expression; Ribosomal scanning and start codon recognition; Translation initiation complex formation
Gene Ontology:
Molecular function: protein binding; RNA binding; translation initiation factor activity; molecular adaptor activity; nucleic acid binding; translation initiation factor binding
Biological process: IRES-dependent viral translational initiation; regulation of translational initiation; translational initiation; viral translational termination-reinitiation; formation of cytoplasmic translation initiation complex; cytoplasmic translational initiation
Cellular component: cytoplasmic stress granule; cytosol; eukaryotic translation initiation factor 3 complex; extracellular exosome; cytoplasm; eukaryotic 43S preinitiation complex; eukaryotic 48S preinitiation complex; eukaryotic translation initiation factor 3 complex, eIF3m; synapse
Genetic constraint (gnomAD): Loss-of-function variants: 5 observed, 97.89 expected, observed/expected ratio (o/e) 0.0511, 90% interval 0.026 to 0.11. The synonymous counts are far from expectation, so gnomAD's model fits this gene poorly and the ratio says little. Missense variants: 900 observed, 975.93 expected, observed/expected ratio (o/e) 0.92, 90% interval 0.87 to 0.97. Synonymous variants: 489 observed, 356.74 expected, observed/expected ratio (o/e) 1.37, 90% interval 1.27 to 1.48.
Homologues: Orthologues: chimpanzee EIF3B (98% identical), mouse Eif3b (91% identical), macaque EIF3B (91% identical), dog EIF3B (90% identical), guinea pig EIF3B (90% identical), guinea pig EIF3B (89% identical), pig EIF3B (89% identical), rat Eif3b (88% identical), rabbit EIF3B (81% identical), tropical clawed frog eif3b (73% identical), zebrafish eif3ba (72% identical), zebrafish eif3bb (71% identical), and 2 more.
Diseases named in the same sentence as EIF3B in open-access papers:
EIF3B is named in the same sentence as 62 diseases in open-access papers, as found by Europe PMC text mining. Sharing a sentence is not in itself a finding about the gene and the disease. The quoted sentences say what the papers report.
prostate carcinoma (14 papers, 2016 to 2025). A carcinoma that arises from epithelial cells of the prostate gland. "EIF3b, a subunit of the eukaryotic initiation factor 3 complex, has been implicated in metastasis in prostate cancer and other solid tumors." (PMID 39247811, 2024). "High EIF3B expression is associated with the development of various cancers, such as gastric cancer, prostate cancer, and osteosarcoma." (PMID 35273605, 2022). "To gain deeper insights into the importance of PUS1 in regulating EIF3b and promoting prostate cancer cell bone metastasis, we integrated data from the TCGA database on PUS1 mutations in prostate cancer." (PMID 39247811, 2024). "This study uncovers a novel regulatory mechanism of the FOXA1/PUS1/EIF3b signaling axis in prostate cancer bone metastasis." (PMID 39247811, 2024). "In summary, our study confirms that PUS1 interacts with EIF3b, suppressing TTC3-mediated ubiquitination degradation, thereby identifying PUS1 as a novel protective molecule of EIF3b, mediating prostate cancer metastasis both in vitro and in vivo." (PMID 39247811, 2024). "Given the important role of EIF3b in prostate cancer 24, 25, we focused on the contribution of EIF3b to PUS1-mediated prostate cancer metastasis." (PMID 39247811, 2024). "Despite detailed elucidation of EIF3b's oncogenic role in prostate cancer, the regulatory mechanisms governing its expression are still under investigation." (PMID 39247811, 2024). "The previous study showed that EIF3B expression was related to human bladder and prostate cancer prognosis, which was responsible for tumor growth and thus worked as an attractive therapeutic target." (PMID 33996561, 2021). "Theodorescu’s group identified eukaryotic initiation factor 3 subunit B (EIF3B) expression elevated in human bladder and prostate cancers." (PMID 29050215, 2017). "Overexpression of eIF3b has been observed in breast, bladder, and prostate cancers; however, the specific mechanism through which upregulated eIF3b promotes the cancer state is still unclear." (PMID 28083147, 2016). "Elevated expression of eukaryotic translation initiation factor 3b (eIF3b) correlates to human bladder and prostate cancer progression." (PMID 26848623, 2016). "Overall, our data suggest that the FOXA1/PUS1/EIF3b signaling axis may serve as an effective therapeutic target for treating prostate cancer bone metastasis." (PMID 39247811, 2024). "Our findings highlight the FOXA1/PUS1/EIF3b axis as a critical mediator of prostate cancer bone metastasis and suggest that targeting this pathway could be a promising therapeutic strategy." (PMID 39247811, 2024). "EIF3B, which is abnormally expressed in various human cancers and plays a crucial role in tumor growth, has been studied in different cancer types, including glioblastoma, bladder cancer, esophageal squamous cell carcinoma and prostate cancer." (PMID 38687509, 2024). "Eukaryotic translation initiation factors 3B (EIF3B), serving as a scaffolding subunit, has been verified to be overexpressed in colon cancer, bladder and prostate cancer, glioblastoma, etc. and also made difference in the biological characteristics of cancer cells." (PMID 27270324, 2016). "In lethal prostate cancer, MITF functions as a transcriptional repressor of eukaryotic initiation factor 3B (eIF3B)." (PMID 41114928, 2025). "In prostate cancer, CircPDE5A regulates EIF3C (a paralog of EIF3B) to suppress m6A methylation of EIF3C mRNA, indirectly influencing MAPK signaling." (PMID 40691141, 2025). "Mechanistically, PUS1 exerts a non-enzymatic function by directly binding to and stabilizing EIF3b, protecting it from TTC3-mediated ubiquitination and degradation, thereby promoting prostate cancer metastasis." (PMID 39247811, 2024). "Eukaryotic initiation factor 3b (eIF3b) was discovered to promote tumor cell proliferation and progression in NSCLC, and also correlated with advanced stages in bladder and prostate cancer." (PMID 36193203, 2022).
prostate carcinoma (continued). "Multiple components of the EIF3 are now known to be dysregulated in multiple cancers (EIF3A in breast, cervical, lung and gastric cancers; EIF3B in breast and gastric cancers; EIF3C in testicular cancers; and EIF3H in prostate cancers)." (PMID 35528200, 2022). "To elucidate the degradation pathway of EIF3b, we employed inhibitors targeting these pathways, namely the ubiquitin-proteasome pathway inhibitor MG132 and the autophagy inhibitor bafilomycin (Baf), in PUS1-knockdown prostate cancer cells." (PMID 39247811, 2024).
gastric cancer (11 papers, 2019 to 2025). A primary or metastatic malignant neoplasm involving the stomach. "EIF3B expression was upregulated in gastric cancer tissues and is associated with poor outcomes in gastric cancer patients." (PMID 35008908, 2022). "In addition, we also examined the expression of eIF3b and its correlation with clinicopathological parameters in clinical tissue samples; this provides a basis for evaluating eIF3b as a potential diagnostic or prognostic marker for gastric cancer." (PMID 31423012, 2019). "For instance, in gastric cancer, EIF3B activates the PI3K/AKT/mTOR pathway by enhancing mTORC1 signaling, indirectly modulating MAPK activity." (PMID 40691141, 2025). "EIF3B is also an oncogene in gastric cancer, lung cancer, osteosarcoma, esophageal squamous cell carcinoma, leukemia and renal cancer." (PMID 35459206, 2022). "The oncogenic role of EIF3B has been widely reported in gastric cancer, esophageal carcinoma and bladder cancer." (PMID 35459206, 2022). "The role of EIF3B as a biomarker of poor prognosis has been reported in gastric cancer, lung cancer, glioma, ovarian cancer and renal cancer." (PMID 35459206, 2022). "Knockdown of EIF3B in gastric cancer cells suppressed the growth of xenograft tumors and lung metastatic colonization in vivo." (PMID 35008908, 2022). "EIF3B promoted gastric cancer cell proliferation, enhanced tumor cell migration and invasion through epithelial-mesenchymal transition (EMT) and the Stat3 signaling pathway in numerous human cancers." (PMID 35008908, 2022). "The results show that the mRNA expression of eIF3b was higher in the gastric cancer cell lines SGC7901 and MGC803 compared with the mRNA expression in the other cell lines." (PMID 31423012, 2019). "A transwell assay was used to detect the effect of eIF3b inhibition on the migration and invasion of gastric cancer cells." (PMID 31423012, 2019). "The immunohistochemistry results show that the eIF3b protein was overexpressed in gastric cancer tissues, and its expression was mainly distributed in the cytoplasm." (PMID 31423012, 2019). "Both cell line and animal studies have suggested a role for eIF3b in the development of gastric cancer." (PMID 31423012, 2019). "We first demonstrated that silencing eIF3b expression affected the proliferation, migration and invasion abilities of gastric cancer cells." (PMID 31423012, 2019). "A wound-healing assay was used to detect the effect of downregulating eIF3b expression on the migration of gastric cancer cells." (PMID 31423012, 2019). "According to our results, compared with that in normal gastric tissues, the eIF3b mRNA expression was increased in gastritis tissues and gastric cancer tissues." (PMID 31423012, 2019). "We were interested in analysing if the effect of eIF3b on gastric cancer cells depends on the translation functions of eIF3." (PMID 31423012, 2019). "From the analysis of these genes in gastric cancer-related signalling pathways, we found that the regulatory trend of the IL-8 protein due to eIF3b inhibition is inconsistent between the SGC7901 and MGC803 cells." (PMID 31423012, 2019). "In gastric cancer cells, after interference with the expression levels of eIF3b, E2F1, cyclin D and cyclin E was downregulated." (PMID 31423012, 2019). "We found that eIF3b inhibition downregulated the expression of some types of protein but upregulated the expression of others in gastric cancer cells." (PMID 31423012, 2019). "The subcutaneous injection test indicated that the downregulation of eIF3b inhibited the proliferation of gastric cancer cells in vivo." (PMID 31423012, 2019). "From those analyses, we concluded that the downregulation of eIF3b inhibited the metastasis of gastric cancer cells in vivo." (PMID 31423012, 2019).
gastric cancer (continued). "In summary, our study reveals the role of eIF3b in the development of gastric cancer at both the in vivo and in vitro levels." (PMID 31423012, 2019). "We found that, compared with those of the control groups, SGC7901 and MGC803 cells with eIF3b inhibition showed low proliferative abilities, indicating that the downregulation of eIF3b inhibited the proliferation of gastric cancer cells." (PMID 31423012, 2019). "CCK-8 and colony-formation assays were used to verify the effects of the downregulation of eIF3b on the proliferation of gastric cancer cells." (PMID 31423012, 2019). "Downregulation of EIF3B inhibited proliferation and metastasis of gastric cancer." (PMID 35008908, 2022). "EIF3B may function as an oncogenic protein that activates the PI3K/AKT/mTOR pathway in gastric cancer." (PMID 36051357, 2022). "In addition, we analysed the correlation between the mRNA expression of eIF3b and the clinicopathological parameters of patients with gastric cancer." (PMID 31423012, 2019). "To verify our speculation, we downregulated eIF3b expression in AGS cells (a gastric cancer cell line with wild-type P5330)." (PMID 31423012, 2019). "However, more studies are needed to address the specific regulatory mechanism of eIF3b in gastric cancer." (PMID 31423012, 2019). "To further verify that the downregulation of eIF3b indeed regulated the proliferation and metastasis of gastric cancer cells by affecting the expression levels of key genes, we selected E2F1, whose expression was dramatically decreased by eIF3b inhibition, to perform the rescue experiments." (PMID 31423012, 2019). "Whether eIF3b cooperates with other eIF3 subunits to promote gastric cancer progression needs to be further studied." (PMID 31423012, 2019). "In addition, the expression of eIF3b correlated with the stage and progression of gastric cancer and was shown to be upregulated in human chronic gastritis and in gastric cancer tissues compared with the expression of eIF3b in normal gastric tissues." (PMID 31423012, 2019). "First, our study found that the downregulation of eIF3b could inhibit the proliferation and metastasis of gastric cancer cells by regulating the expression of cancer-related genes." (PMID 31423012, 2019). "We also found that eIF3b could affect the expression of β-catenin and vimentin in gastric cancer cells." (PMID 31423012, 2019). "For eukaryotic translation initiation factor 3, subunit B (EIF3B) expression was found to be upregulated in gastric cancer tissues; it is strongly associated with proliferating cell nuclear antigen (PCNA) expression and is associated with poor outcomes in gastric cancer patients." (PMID 35008908, 2022). "Therefore, this study aimed to investigate the role of eIF3b in the development of gastric cancer." (PMID 31423012, 2019). "Thus, we detected eIF3b expression in gastric cancer cells in the presence of H. pylori." (PMID 31423012, 2019). "Moreover, Helicobacter pylori (H. pylori) infection could upregulate the expression of eIF3b in gastric cancer cells, suggesting that eIF3b might be involved in the carcinogenic process of H. pylori." (PMID 31423012, 2019). "EIF3B promotes tumor migration and metastasis by activating the PI3K/ AKT/ mTOR pathway during the development of gastric cancer." (PMID 38406279, 2024). "Cell proliferation, migration, and invasion are inhibited when EIF3B is down-regulated in cells of OV, STAD (gastric cancer), NSLC (non-small cell lung cancer), ESCC (esophageal squamous cell carcinoma), and ccRCC (clear cell renal cell carcinoma)." (PMID 35040374, 2022). "qRT-PCR was used to detect the expression of eIF3b mRNA in the human immortalized gastric epithelial cell line GES-1 and in five other gastric cancer cell lines, AGS, SGC7901, MGC803, BGC823 and HGC27." (PMID 31423012, 2019). "We will further investigate whether eIF3b affects cell invasion and migration through EMT or the Wnt/β-catenin pathway in gastric cancer." (PMID 31423012, 2019).
gastric cancer (continued). "The qRT-PCR results show that the eIF3b mRNA levels in gastric cancer tissues were higher than those in non-tumorous adjacent tissues." (PMID 31423012, 2019). "Several studies have shown that eIF3b can affect the development of cancer, but the role of eIF3b in gastric cancer is not clear." (PMID 31423012, 2019). "The immunohistochemistry results show that the expression of the eIF3b protein in gastric cancer tissues was significantly higher than that in non-tumorous adjacent tissues and that eIF3b was mainly expressed in the cytoplasm." (PMID 31423012, 2019). "In accordance with the present results, previous studies have demonstrated that EIF3B downregulation suppresses cell proliferation, migration and invasion, and induces cell apoptosis by blocking the β-catenin pathway in endometrial cancer or the PI3K/AKT/mTOR pathway in gastric cancer." (PMID 35040374, 2022). "Moreover, the inhibition of eIF3b expression can also regulate the mRNA expression level of some genes in gastric cancer (data not shown)." (PMID 31423012, 2019). "However, the expression of eIF3b and its effect on the progression of gastric cancer have not yet been reported." (PMID 31423012, 2019).
glioma (7 papers, 2013 to 2023). A benign or malignant brain and spinal cord tumor that arises from glial cells (astrocytes, oligodendrocytes, ependymal cells). "Protein and mRNA expressions of eIF3B, eIF3I, eIF4A1, eIF4H, eIF5 and eIF6 were significantly increased in high grade gliomas compared to CCBT and partially in low grade gliomas." (PMID 33807050, 2021). "Recently, systematically profiling found that the expression of eIF3b, eIF3i, eIF3k, and eIF3m was increased with the glioma grade and poorer overall survival." (PMID 32565801, 2020). "The results indicated that the expression levels of eIF3a, eIF3b, eIF3i, eIF3k, eIF3l and eIF3m were significantly (P < 0.05) correlated to the OS of glioma patients in both datasets." (PMID 31171919, 2019). "Upregulation of eIF3B was described in glioma patient samples." (PMID 37907716, 2023). "Upregulation of eIF3B has been described previously in glioma patient samples." (PMID 33807050, 2021). "Regarding the eIF3 complex, significantly higher protein expression in gliomas compared to CCBT was detected for eIF3B (III: p < 0.05), eIF3D (I: p < 0.05; III: p < 0.05), eIF3H (III: p < 0.05), eIF3I (I: p < 0.05, III: p < 0.001, IV: p < 0.01) and eIF3M (III: p < 0.01)." (PMID 33807050, 2021). "More studies showed knockdown of EIF3B, decreasing EIF3C, and silencing EIF3D and EIF3E alleviated proliferation and migration of glioma cells." (PMID 32565801, 2020). "In a later study, the same group found that eIF3D is increased in gliomas (n = 35) and that its inhibition in U87MG cells induces similar effects as what they obtained for eIF3B." (PMID 31795417, 2019).